KBTBD8 (kelch repeat and BTB domain containing 8)
Description:
Substrate-specific adapter of a BCR (BTB-CUL3-RBX1) E3 ubiquitin ligase complex that acts as a regulator of neural crest specification. The BCR(KBTBD8) complex acts by mediating monoubiquitination of NOLC1 and TCOF1: monoubiquitination promotes the formation of a NOLC1-TCOF1 complex that acts as a platform to connect RNA polymerase I with enzymes responsible for ribosomal processing and modification, leading to remodel the translational program of differentiating cells in favor of neural crest specification.
Synonyms: TA-KRP; KIAA1842; TAKRP
Tractability: Small molecule: it belongs to a druggable protein family. PROTAC: ubiquitination databases record sites on it.
Gene: Protein-coding gene on chromosome 3 (66,998,307 to 67,011,210, forward strand). Ensembl gene ENSG00000163376.
Subcellular location: Cytoplasm, cytoskeleton, spindle; Golgi apparatus
Pathways (Reactome):
Immune System: Antigen processing: Ubiquitination & Proteasome degradation
Metabolism of proteins: Neddylation
Gene Ontology:
Molecular function: protein binding; ubiquitin-like ligase-substrate adaptor activity
Biological process: neural crest cell development; neural crest formation; protein monoubiquitination; proteasome-mediated ubiquitin-dependent protein catabolic process
Cellular component: Cul3-RING ubiquitin ligase complex; Golgi apparatus; cytoplasm; cytosol; spindle
Genetic constraint (gnomAD): Loss-of-function variants: 27 observed, 53.45 expected, observed/expected ratio (o/e) 0.51, 90% interval 0.37 to 0.7. The upper end of that interval is the gene's LOEUF score, 0.7, which puts it in group 2 of 6, group 1 being the genes least tolerant of losing a copy. Missense variants: 629 observed, 760.34 expected, observed/expected ratio (o/e) 0.83, 90% interval 0.77 to 0.88. Synonymous variants: 244 observed, 258.15 expected, observed/expected ratio (o/e) 0.95, 90% interval 0.85 to 1.05.
Homologues: Orthologues: chimpanzee KBTBD8 (99% identical), macaque KBTBD8 (99% identical), dog KBTBD8 (98% identical), mouse Kbtbd8 (97% identical), pig KBTBD8 (97% identical), rat Kbtbd8 (97% identical), guinea pig KBTBD8 (94% identical), tropical clawed frog kbtbd8 (78% identical), zebrafish kbtbd8 (73% identical). Paralogues in human: KBTBD2 (34% identical), KLHL24 (26% identical), KLHL6 (26% identical), KBTBD12 (25% identical), KBTBD7 (25% identical), KBTBD6 (25% identical), IPP (24% identical), KLHL12 (24% identical), KLHL40 (24% identical), KLHL20 (24% identical), KLHL41 (23% identical), KLHL17 (23% identical), and 42 more.
Diseases named in the same sentence as KBTBD8 in open-access papers:
KBTBD8 is named in the same sentence as 10 diseases in open-access papers, as found by Europe PMC text mining. Sharing a sentence is not in itself a finding about the gene and the disease. The quoted sentences say what the papers report.
anaphylaxis (1 paper, 2019). An acute hypersensitivity reaction that occurs from exposure to an allergen. "This approach identified several genes that are associated with aging (ATP2B2, CAV3, CNTN3, CTNNA2, GRID2), inflammation (ATP2B2, CAV3, RAD18, KBTBD8), vascular permeability (SFXN5, RAD18) and anaphylaxis (CAV3, RAD18, CTNNA2, ATP2B2 and GRID2)." (PMID 31701027, 2019).
melanoma (1 paper, 2018). A malignant, usually aggressive tumor composed of atypical, neoplastic melanocytes. "Conversely, inhibition of CK2 might provide therapeutic benefit against melanoma, a cancer driven by aberrant expression of KBTBD8." (PMID 29999490, 2018). "Underscoring the importance of this regulatory circuit for human biology, mutations in TCOF1 account for ~90% of cases of the craniofacial disease Treacher Collins Syndrome, while additional transcription factor binding sites in the promoter of KBTBD8 drive melanoma, a cancer of neural crest origin." (PMID 29999490, 2018).
ovarian carcinoma (1 paper, 2020). A malignant neoplasm originating from the surface ovarian epithelium. "Western blot analysis also showed that KBTBD8 protein levels in ovarian cancer tissue were approximately fourfold higher than that in normal ovarian tissue (to make sentences concise, we included all exact values into the figure legends)." (PMID 33109073, 2020). "In the present study, we found for the first time that KBTBD8 was significantly upregulated in various clinical human ovarian cancer tissues and cultured cell lines." (PMID 33109073, 2020). "KBTBD8 overexpression is positively correlated with the malignancy grade of ovarian cancer." (PMID 33109073, 2020). "We first evaluated KBTBD8 protein levels using immunohistochemistry on a human ovarian cancer tissue microarray and found that KBTBD8 levels were highly correlated with the malignancy grade of ovarian cancer." (PMID 33109073, 2020). "Moreover, we also verified that KBTBD8 knockdown significantly reduced the overall protein ubiquitination of ovarian cancer cells." (PMID 33109073, 2020). "However, there have been no reports on the role of KBTBD8 in the progression of epithelial ovarian cancer, EOC." (PMID 33109073, 2020).
ovarian tumor (1 paper, 2020). "Finally, KBTBD8 knockdown significantly diminished ovarian tumor formation in vivo." (PMID 33109073, 2020).
cancer (6 papers, 2017 to 2023). A tumor composed of atypical neoplastic, often pleomorphic cells that invade other tissues. "In addition to TERT, BLCAP, and KBTBD8, we also observed low levels of damage induction in UV-irradiated melanocytes at a number of other recurrent mutations in the promoters of known or suspected cancer genes (i.e., TCF3, TOP2A, NUMB, FOSB, and OTUB2)." (PMID 37169747, 2023). "GULP1 is located on SSC15 and plays key roles in cancer suppression and immune responses, whereas KBTBD8 is involved in cytoskeleton arrangement, regulation of cell morphology, and idiopathic short stature." (PMID 33705632, 2021). "HOTS overexpression inhibits the growth of multiple types of cancer, while HOTS knockdown increases tumor progression in vitro, in accordance with sequencing results where KBTBD8 knockdown caused HOTS upregulation." (PMID 33109073, 2020). "Notably, the recurrent promoter mutation in BLCAP, a suspected cancer gene, is also predicted to create an ETS binding site, while KBTBD8 plays a critical role in melanocyte differentiation." (PMID 37169747, 2023). "We have to note that nude mice, although widely used in cancer studies, are immunodeficient and may not fully reflect the actual immunity situation of the host, but the sharp decrease in tumor growth appears to be the effect of KBTBD8 knockdown." (PMID 33109073, 2020).
tumor (1 paper, 2020). "KBTBD8 knockdown significantly reduced tumor formation in nude mice." (PMID 33109073, 2020).
KBTBD8 also shares sentences with these, for which no sentence is quoted: diabetes (1 paper); neuroblastoma (1); neurodegenerative disease (1); Treacher-Collins syndrome (1).